MCL1 (MCL1 apoptosis regulator, BCL2 family member)
Diseases named in the same sentence as MCL1 in open-access papers (continued):
Sharing a sentence is not in itself a finding about the gene and the disease.
melanoma (continued). "Finally, depletion of MCL-1 promotes anoikis in BRAFV600 melanoma cells." (PMID 27846237, 2016). "During our analysis of the CDKN2a locus in malignant melanoma we discovered that upregulation of the pro-survival gene MCL-1 was associated with loss of ARF, a relatively common occurrence in melanoma, providing some explanation for the characteristically chemo-resistant behavior of most melanomas." (PMID 27846237, 2016). "The outcome of treatment with PN, cell death or senescence, might also depend on other molecules crucial for melanoma proliferation and survival such as MCL-1, and therefore melanoma tumors have to be molecularly characterized to select appropriate drugs for combined treatment." (PMID 26824319, 2016). "Survival of melanoma cells after cell detachment may depend on MCL-1." (PMID 26035829, 2015). "Preclinical data in melanoma mouse xenografts and osteosarcoma cells, showed that dinaciclib induces apoptosis, increases Bax and Bim in mitochondria, and decease antiapoptotic factors, such as Mcl-1, Bcl-2, Bcl-xL and XIAP, as well as phosphorylation of Ser2 of RNA Pol II." (PMID 25596730, 2015). "Therefore, targeting of BCL-2-like proteins is an interesting option in anticancer therapy, and our study points to the involvement of MCL-1, especially in MITFhigh populations, in phenotypic plasticity of melanoma cells used in immediate adaptation to modifications of the microenvironment." (PMID 26035829, 2015). "As induction of [Ca2+]i by thapsigargin has been described to increase Mcl-1 transcription in melanoma, we evaluated if calcium modulation could target Mcl-1 transcription in our models; however results suggest that this mechanism does not seem to be involved in ovarian carcinoma cells." (PMID 25627260, 2015). "Notably, trametinib treatment also induced Mcl-1 expression in all the melanoma cell lines tested." (PMID 26497853, 2015). "In melanomas, the anti-apoptotic proteins Bcl-2, Bcl-xL, and Mcl-1 appear to increase while the pro-apoptotic protein Bax decreases with the progression of primary melanoma tumors and melanoma cells and might be involved in resistance to conventional therapies." (PMID 24647338, 2014). "The anti-apoptotic Mcl-1 is an important member of the apoptosis regulating Bcl-2 family and has been shown to be overexpressed in variety of cancers including, cervical, ovarian, pancreatic, hepatocellular, non-small cell lung, testicular germ cell cancers and melanomas." (PMID 25409302, 2014). "Indeed, Noxa contributes to induction of apoptosis of melanoma cells when Mcl-1 is inhibited." (PMID 25365078, 2014). "Thus, Mcl-1 may play a critical role in the initiation of melanoma development and seems to be a suitable molecular target to enhance chemo-sensitivity of this dreaded disease." (PMID 24223823, 2013). "Taken together, these data suggest that the pro-apoptotic synergy between Maritoclax and ABT-737 is, at least in part, due to the degradation of Mcl-1 induced by Maritoclax and simultaneous inhibition of Mcl-1 and Bcl-2 may be an effective strategy for melanoma therapy." (PMID 24223823, 2013). "The suppression of Mcl-1 inhibited the proliferation of a wide variety of human tumor cells, including prostate cancer, pancreatic cancer, small-cell lung cancer, ovarian cancer, chronic lymphocytic leukemia, hepatoma, leukemia, chronic lymphocytic leukemia, breast carcinoma, and melanoma." (PMID 24223823, 2013). "Therefore, down-regulation of Mcl-1 by inhibition of phosphorylated STAT3 may be an important mechanism of action of SOID-8 in these melanoma cells." (PMID 23166634, 2012). "Interestingly, Mcl-1 has been shown to be an important melanoma anti-apoptotic protein." (PMID 19274086, 2009). "We next determined whether Mcl-1 knockdown alone could reduce viability of melanoma cells." (PMID 19684859, 2009).
melanoma (continued). "A triple combination of S63845, venetoclax, and parthenolide (a NOXA inducer and MCL1 suppressor) further enhances apoptosis by suppressing MITF, a key regulator of melanoma plasticity." (PMID 41155156, 2025). "Co-inhibition of MCL1 with BCL2 or BCLXL induces apoptosis in both bulk melanoma cells and therapy-resistant melanoma-initiating cells." (PMID 41155156, 2025). "Furthermore, immunoblotting analysis of a panel of melanoma cell lines suggested a correlation between basal mTORC1 activity and the levels of MCL1-but not Bcl-2-in most of those cells, suggesting that MCL1 may play a role in regulating mTORC1 basal activity." (PMID 41326406, 2025). "In contrast to monotherapy with BH3-mimetics, the combination of Mcl-1 inhibitors with Bcl-2 inhibitors showed promising activities against BRAFV600E-mutant and BRAF-wildtype melanomas." (PMID 39935431, 2025). "Overexpression of miR-596 in melanoma effectively inhibited the MAPK/Erk signaling pathway by downregulating MEK1, MCL1 and BCL2L1 levels." (PMID 40282319, 2025). "Using two human phospho-kinase profiler kits, we examined the phosphorylation of a wide array of key signaling kinases shortly upon depleting MCL1 in CHL-1 cells, a melanoma cell line that expresses high levels of MCL1." (PMID 41326406, 2025). "The combination of this MCL1 inhibitor and anti-PD-1 therapy in these mouse models showed enhanced inhibition of melanoma growth and improved CD8+ T cell activation compared to treatment with single agent MCL1 inhibitor or anti-PD-1." (PMID 38459020, 2024). "In melanoma cells, cleavage of caspase-3 and PARP were reported when cells were treated with the Mcl-1 inhibitor A-1210477 in combination with ABT-263, and in activity assays, activated caspase-3/7 was reported after combined S63845/ABT-263 treatment." (PMID 38542429, 2024). "Recently, many have shown that targeting BCL-xL and MCL-1 in combination, is highly efficacious in variety of solid disease settings such as cervical cancer, MPM, melanoma and non-small cell lung cancer." (PMID 37210412, 2023). "To challenge trametinib-resistant melanoma cells, we used S63845, a synthetic inhibitor of MCL-1 that has been designed to specifically bind to BH3-binding groove of MCL-1." (PMID 37835493, 2023). "The downregulation of STAT3-targeted genes MCL-1, MMP-2, MMP-9, and VEGF, which promote cell growth, migration, and invasion, have been identified in melanoma cells after quercetin treatment." (PMID 36829966, 2023). "The results suggested that in certain melanoma cells, the pro-survival proteins BFL-1, MCL-1 and BCL-XL are all responsible for cell survival." (PMID 35900226, 2022). "Synergistic anti-neoplastic effects of the metformin/hypoglycemia combination were regulated by PP2A-GSK3β-MCL-1 axis, leading to a decline in the pro-survival protein MCL-1 and reduction in tumor growth in in vitro and in vivo metastatic melanomas models." (PMID 35745105, 2022). "The same trend was observed in melanoma cells treated with EPI, which significantly increased the mRNA expression of BAX and decreased the mRNA expression of BCL2, BIRC5, and MCL-1." (PMID 35877720, 2022). "Our findings identified BFL-1 as a factor that mediates resistance to combined MCL-1 and BCL-XL inhibition in certain melanoma cells." (PMID 35379799, 2022). "To this regard, we observed that melanoma as well as NSCLC cells, having relative higher levels of endogenous Bcl-2 and Mcl-1 proteins, respect to breast and colon cancer cells, were more sensitive to treatment." (PMID 35265218, 2022). "In A375 melanoma cells, knockdown of CD274, MCL1, and JUNB decreased cell survival, and in OAW28 ovarian cystadenocarcinoma cells, knockdown of MCL1 and JUNB decreased cell survival." (PMID 35338135, 2022). "Our screen identifies four candidate genes (CD274 (PD-L1), MCL1, JUNB, and B3GNT2) that, upon upregulation, enable human melanoma cells to evade T cell killing in diverse cancer cell types and mouse xenografts." (PMID 35338135, 2022).
melanoma (continued). "Combined inhibition of MCL-1 and BCL-xL by S63845/S64315 plus Navitoclax or the combination of MCL-1 and BCL-2 by S63845/S64315 plus ABT-199 synergistically induces extensive death in advanced/refractory melanoma cell lines both in vitro and in vivo." (PMID 33883020, 2021). "One of the first small molecules used in melanoma was the pan BH3 inhibitor obatoclax (GX15-070), showing affinity for Bcl-2, Bcl-xL, Mcl-1, Bcl-w and A1/Bfl-1." (PMID 33803452, 2021). "The dual BCL-XL/BCL-2 inhibitor Navitoclax was also shown to synergise with BETi in small cell lung cancer, colorectal cancer, glioma and B-cell lymphomas, whilst BH3-mimetics targeting MCL-1 enhance BETi activity in AML and melanoma." (PMID 33799592, 2021). "The anti-apoptotic BCL-2 proteins, including MCL-1 and BCL-XL, play a critical role in the survival of these hard-to-treat melanoma cells." (PMID 34575429, 2021). "A combination of the MCL-1 blocker S63845 and the BCL-XL blocker navitoclax acted synergistically to attenuate different types of melanoma cells in vitro and in vivo." (PMID 34575429, 2021). "We assessed the effects of MCL1 inhibitors (MCL1i; S63845, S64315) in combination with AZA in cutaneous and rare melanoma subtypes." (PMID 34451846, 2021). "Overall, these data suggest that a treatment combining MCL1 inhibition and AZA is most beneficial for melanoma patients from the rare mucosal and uveal subtypes, for which there are limited treatment options currently available." (PMID 34451846, 2021). "Here, enhancing NOXA levels, suppressed the anti-apoptotic actions of Mcl1 and override resistance to ABT-737, with Vorinostat, Vinblastine, Bortezomib, Dinaciclib co-treatments in SCLC, CLL and melanoma cells." (PMID 34753495, 2021). "At 72 hours following miR transfection, expression of MCL1 was decreased in the A375 and MEL39 melanoma cell lines." (PMID 34469478, 2021). "Compared to other cancers, the MCL-1:BCL-xL mRNA and protein ratio was 2 to sixfold higher in melanoma." (PMID 33308268, 2020). "Taken together, these combinations, targeting MCL1 plus BCLXL, offer alternative options for many difficult-to-treat melanomas, and should be tested as a treatment for patients with resistant or relapsed disease." (PMID 32513939, 2020). "We used genetic knockdown and pharmacologic approaches of BH3 mimetics to target anti-apoptotic BCL2 family members and identified MCL1 and BCLXL as crucial pro-survival members in melanoma." (PMID 32513939, 2020). "Mcl-1 expression can be increased by STAT3 pathway in cholangiocarcinoma cells 20, colorectal cancer cells 22, melanoma cells 28 and gastric cancer cells." (PMID 31956373, 2020). "Our data showed that shikonin inhibited the expression levels of antiapoptotic proteins Bcl-2 and Mcl-1, and enzymatic activities of collagenases MMP-2 and MMP-9, which play vital roles in melanoma metastasis." (PMID 32536866, 2020). "As such, MCL-1 inhibitors strongly sensitized BRAF and NRAS driven melanoma cell lines to inhibition of the RAF-MEK-ERK pathway, more so than inhibitors of BCL-2/BCL-XL, and more so than in ERK pathway-driven colorectal cancer cell lines." (PMID 31988312, 2020). "The aim of this study was to assess the effect of MIM1 a specific low molecular Mcl-1 protein inhibitor and mixture of MIM1 and dacarbazine on the viability, cell cycle progression and apoptosis induction in amelanotic C32 melanoma cells." (PMID 31432325, 2020). "Our genetic knockdown of several BCL2 family members in combination with BH3 mimetics highlights the role of MCL1 and BCLXL in melanoma cells." (PMID 32513939, 2020). "Strikingly, combining the direct and potent MCL1 inhibitor S63845 with A-1331852 or ABT-263, resulted in exceptional killing in relapsed or resistant melanomas at below 200 nM." (PMID 32513939, 2020). "Taken together, this study suggests that dual targeting of MCL1 and BCLXL should be considered as a treatment option for difficult-to-treat melanoma patients." (PMID 32513939, 2020).
melanoma (continued). "Our in vitro data suggested that the combination of an MCL1 inhibitor and ABT-199 was effective against all melanomas, but higher concentrations were necessary for the BRAF-MUT compared to the BRAF-WT." (PMID 32764384, 2020). "Further study showed that shikonin decreased the levels of STAT3-targeted genes Mcl-1, Bcl-2, MMP-2, vimentin, and Twist, which are involved in melanoma survival, migration, and invasion." (PMID 32536866, 2020). "If this pattern holds true, combination treatments against MCL1 and BCLXL are an especially attractive therapy against advanced melanomas." (PMID 32513939, 2020). "In melanoma, knocking down BCL2 sensitized cells to the MCL1 inhibitor S63845, and conversely knocking down MCL1 sensitized cells to the BCL2 inhibitor ABT-199." (PMID 32764384, 2020). "We and others have previously shown that most melanoma cell lines express the major anti-apoptotic BCL2 family member proteins, such as BCL2, MCL1, and BCLXL10–15." (PMID 32513939, 2020). "Our data with BH3-mimetics demonstrate the importance of targeting MCL-1 and BCL-XL to achieve potent killing of melanoma cells." (PMID 31019203, 2019). "On the basis of above finding it is concluded that FEO exhibited in vitro anti-melanoma activity by reducing the viability in B16-F10 cell, FM94 cells and not in HNEM cells by the induction of apoptosis via caspase signaling and MCL-1 dependent pathway." (PMID 31191820, 2019). "The contribution of the increased NOXA levels to the apoptosis observed was assessed by overexpressing MCL1, the selective target of NOXA, in A2058 melanoma cells." (PMID 31044505, 2019). "Treatment of BRAF-mutant primary melanoma cells with up to 24 h of BRAF, MEK, or ERK inhibitors induced MCL-1 dependence." (PMID 31727958, 2019). "The same analysis in CRC and melanoma patient-derived xenograft (PDX) samples demonstrated markedly low BCL-XL expression in melanoma PDXs vs. CRC, whereas MCL1 expression was broadly similar." (PMID 31727888, 2019). "Concomitant treatment with the MCL-1 inhibitor and BRAF inhibitor had modest synergy in A375M melanoma cells." (PMID 31727958, 2019). "Here, we have conclusively identified MCL-1 and BCL-XL as the pro-survival proteins most critical for melanoma cell survival and co-targeting them results in synergistic killing." (PMID 31019203, 2019). "We found that concomitant treatment of melanoma cells with inhibitors of BRAF and MCL-1 was also less effective than sequential treatment." (PMID 31727958, 2019). "While BCL2 expression was higher in melanoma, BCL2 mRNA levels (RNA-seq read number) were very low in each lineage relative to MCL1 and BCL-XL." (PMID 31727888, 2019). "There are already studies evaluating melanoma and thyroid carcinoma showing the reduction of BCL-2 and MCL-1 expression in people using propranolol." (PMID 30018638, 2018). "Among the few endogenous miRNAs upregulated in miR-576-5p transfected melanoma cells, we detected miR-548f which targets GFI1, representing a transcriptional repressor of MCL1." (PMID 30197759, 2018). "We tested the efficacy of the BH3 mimetic combination of A-1210477 (an MCL-1 inhibitor) and ABT-263 (a BCL-2/BCL-XL/BCL-W inhibitor) in killing melanoma, especially MICs." (PMID 30185782, 2018). "Melanomas overexpresses multiple anti-apoptotic BCL-2 family members, and in particular, MCL-1 plays a crucial role in promoting resistance." (PMID 30185782, 2018). "While BCL-XL overexpressing clones show superimposable expression level of MCL-1 protein when compared to control clones, a reduced expression of BCL-2 protein was observed in both melanoma and glioblastoma models." (PMID 29238043, 2017). "In this study we tested the efficacy of an MCL-1 inhibitor, SC-2001, either alone or in combination with ABT-737 in killing melanoma cells and MICs." (PMID 27086916, 2017).
melanoma (continued). "Taken together, this work is of interest to both clinicians and researchers due to its following novelties: 1) Targeting MCL-1 and other BCL-2 family members is a promising approach to kill the bulk of melanoma cells, and most importantly, also the MICs." (PMID 27086916, 2017). "This study is the first to examine the efficacy of MCL-1 and BCL-2 inhibitors in combination to induce killing of both bulk melanoma cells and MICs." (PMID 27086916, 2017). "Our results also confirm the important roles of both proteins in antagonizing MCL-1 in melanoma, and that indeed NOXA-MCL-1-BIM axis can play a crucial role in the combination-induced killing of melanoma cells including the MICs." (PMID 27086916, 2017). "TRAIL-induced MCL-1 inhibition leads to BIM-mediated apoptosis and low levels of BIM contribute to melanoma's resistance to BRAF inhibitors." (PMID 27829238, 2016). "Survivin, BCL-XL, and MCL-1 have been identified as STAT3- targeted genes, which played important roles in melanoma cell growth and survival." (PMID 27323414, 2016). "In melanoma, HDAC inhibitors inhibit expression of anti-apoptotic proteins survivin, Bcl-XL, Bcl-2, Mcl-1, XIAP, mostly via decreased transcription." (PMID 26426052, 2015). "MCL-1 is cooperatively regulated by MEK and mTOR in the MEK driven OCM1A melanoma cell line, and mTOR is known to induce cell survival through upregulation of MCL-1 protein." (PMID 25955301, 2015). "Immediate adaptive response of melanoma cells selectively involves a temporary MCL-1 increase, both at mRNA and protein levels, and BCL-XL can complement MCL-1, especially in MITFlow populations." (PMID 26035829, 2015). "In melanomas, ETS-1 has been recently identified as a key factor in upregulation of Mcl-1 gene, upon endoplasmic reticulum stress, and thus in the resistance of melanoma cells to apoptosis." (PMID 24086527, 2013). "As the melanoma cells were shown to be markedly more resistant to ABT-737 than Obatoclax, we used siRNA to knock down expression of Mcl-1, known to be the major difference between the specificity of both agents." (PMID 24367627, 2013). "For instance, in melanoma upregulated miR-149 suppressed GSK3-α expression and upregulated Mcl-1 expression, resulting in apoptotic resistance." (PMID 23762558, 2013). "In this study, we investigated the effects of Maritoclax, a novel Mcl-1-selective inhibitor, alone and in combination with ABT-737, on the survival of human melanoma cells." (PMID 24223823, 2013). "It has been shown previously that either Mcl-1 downregulation or NOXA overexpression, an Mcl-1 specific BH3-only protein, strongly sensitizes melanoma cells to ABT-737 in vitro." (PMID 23171055, 2012). "However, it was still unclear whether the decrease in the pro-death Bax and/or the increase in the anti-death Bcl-2, Bcl-xl, and Mcl-1 proteins are merely a defence response against immune and microenvironment challenges, or were necessary for in vivo melanoma progression." (PMID 22233801, 2012). "Immunohistochemical expressions of 12 promising biomarkers (pAkt, Bim, BRG1, BRMS1, CTHRC1, Cul1, ING4, MCL1, NQO1, SKP2, SNF5 and SOX4) were studied in 122 melanomas and 33 dysplastic nevi on tissue microarrays." (PMID 23028750, 2012). "Our previous work has shown that melanoma cells are only slightly sensitive to ABT-737 at high doses, and that this resistance is mediated exclusively through Mcl-1." (PMID 21897876, 2011). "Overall, our studies demonstrate that the combination treatment of Mcl-1 knockdown and ABT-737 is a promising new treatment strategy for melanoma that calls for further investigation in vivo." (PMID 19684859, 2009). "Here we confirm this observation and further provide the first in-depth characterization of the combined effect of Mcl-1 small interfering RNA (siRNA) and ABT-737 in malignant melanoma." (PMID 19684859, 2009).